CDC42 (cell division cycle 42)
Diseases named in the same sentence as CDC42 in open-access papers (continued):
Sharing a sentence is not in itself a finding about the gene and the disease.
breast carcinoma (continued). "It has been reported that hyperactivated Cdc42 (under both normoxic and hypoxic conditions) upregulates VEGF in breast cancer cells." (PMID 30754684, 2019). "miR-23b downregulates the Rac/Cdc42 guanine nucleotide exchange factor 6 (ARHGEF6) which activates Cdc42/PAK, thus enhancing focal adhesions maturation in breast cancer." (PMID 30754684, 2019). "PAK2 is unique among the PAK family: Activated by Cdc42, full-length PAK2 protects breast cancer cells from drug-induced cell death; when proteolytically cleaved by caspase 3, PAK2 generates its fragment PAK2p34 that favors apoptosis." (PMID 30754684, 2019). "There were ceRNA networks that co-regulated cell migration and invasion in breast cancer patients by MALALT1, miR-1 and Cdc42." (PMID 29596304, 2018). "Among the validated proteins, CDC42 and SEPT9 had been found to be greatly increased in multiple tumor tissues, including liver, colorectal, and breast cancer and glioma." (PMID 27708241, 2016). "Since the Rho family GTPases, RhoA and Cdc42, are known modulators of the actin cytoskeleton and play a vital role in EMT and metastasis in breast cancer, we assessed the activity of these GTPases following MDA-9 modulation." (PMID 27863394, 2016). "CDC42 is a candidate cancer driver according to NCG and is also listed in the “Breast cancer” malacard." (PMID 27808240, 2016). "To gain information on how ERK1/2 can mediate its effect on breast cancer cell migration and invasion, we next investigated and demonstrated that WNT‐5A signaling and constitutively active Cdc42 both decreased matrix metalloproteinase 9 (MMP9) activity." (PMID 23727359, 2013). "In the present study, WNT‐5A activated Cdc42 in MDA‐MB468 and MDA‐MB231 breast cancer cell lines (both ATCC‐certified and ‐characterized)." (PMID 23727359, 2013). "We previously demonstrated that exposure to nicotine augmented the migration or invasion ability of benign or malignant breast cancer cell lines, in which PKC and cdc42 played a crucial role." (PMID 22085699, 2011). "PARD6B, an isoform of PAR6, is also elevated in breast cancers in which PAR6 binding to aPKC and CDC42 activates the MEK (mitogen-activated protein kinase kinase)/ERK (extracellular signal-regulated kinase) pathway raising cell proliferation and acinar hyperplasia." (PMID 40057606, 2025). "Furthermore, we identified the Reelin-LRP8 signaling pathway as a key regulatory mechanism in aggressive brain metastatic breast cancer, with LRP8 enhancing CDC42 activation to promote filopodia formation, dependent on Reelin." (PMID 40506610, 2025). "Hence, BEC promote metastatic extravasation through activation of EGFR signalling in breast cancer cells that requires DOCK4, DOCK9, RAC1 and CDC42, rendering them competent for extravasation." (PMID 38762624, 2024). "Recently, Sayedyahossein et al48 reported identification of small molecules that disrupt binding of Cdc42 and IQGAP1 and inhibit proliferation and migration of breast carcinoma cells lending further credence to the approach of targeting the GRD domain of IQGAP1." (PMID 38834690, 2024). "p120 can facilitate the transformed growth of human breast cancer cells through Rac1 activation and Rac1-mediated MAPK signaling, and modulate the invasion and migration of GnRH-induced human ovarian cancer cells through modulating Rac1 and Cdc42." (PMID 39498333, 2024). "Using bioinformatics tools, we found elevated expressions of CDC42 and ACTR2 in breast cancer." (PMID 38612766, 2024). "In addition to NSCLC, depleted levels of RAC1, CDC42, and RHOA were also observed in several other cell lines, including lung cancer (A549 and NCI-H1299) and breast cancer (MDA-MB-468 and MDA-MB-231), following PCAIs treatment." (PMID 38540084, 2024). "Furthermore, both breast cancer cell lines exhibited significant reductions in the levels of KRAS, RHOA, RAC1, and CDC42 proteins of 49, 40, 50, and 48%, respectively in MDA-MB-468 cells." (PMID 36961909, 2023).
breast carcinoma (continued). "Our published data demonstrate that the Vav/Rac inhibitor EHop-016 and the Rac/Cdc42 guanine nucleotide association inhibitor MBQ-167 reduce mammary tumor growth and prevent breast cancer metastasis from pre-clinical mouse models without toxic effects." (PMID 37397366, 2023). "The Cdc42 sensor dimericTomato–WASp(CRIB) accumulated in a spatially restricted manner upon invadopodia formation induced by phorbol ester phorbol 12,13-dibutyrate (PDBu) treatment of SUM159 breast cancer cells." (PMID 37226883, 2023). "Therapeutic targeting of CDC42 affects the proliferation and survival of multiple myeloma cells and the spread of metastasis in breast cancer models with HER2 and triple-negative subtypes of breast cancer." (PMID 37746266, 2023). "The individual expression of the constitutively active mutants, Myc-tagged CDC42 (Myc-CDC42(F28L)), Myc-CDC42b(F28L), or the carboxyl terminally V5-tagged ACK (ACK-V5) did not affect the expression of either mTOR or the EGFR in MDA-MB-231 breast cancer cells (lanes 1–4, columns 1–4)." (PMID 36206843, 2022). "Furthermore, cucurbitacin B acts as a mediator in the distribution and reorganization of cytoskeletal proteins via RAC1/CDC42/RhoA signaling, altering the mechanical properties of MDA‐MB‐231 and SKBR‐3 breast cancer cells." (PMID 36585670, 2022). "Among this PPI network, PTEN, CCND1, VEGFA, CDC42, and EZH2 were ranked as the top five hub genes, which may function as key genes in the m5C regulators-related miRNA–mRNA regulatory network in breast cancer." (PMID 35812757, 2022). "Because the interaction between IQGAP1 and Cdc42 enhances cell proliferation and migration, we examined if small molecules NCGC00131308, NCGC00138812 and MLS000332963 can modulate these functions in breast cancer cells." (PMID 36253497, 2022). "The findings denoted the partiality of miR-29a which exerts its tumor suppressor role in breast cancer cell lines by cessation of the cell cycle through negative regulation of CDC42." (PMID 36140219, 2022). "A study in breast cancer cell line MDA-MB-453 revealed that its expression arrests the cells at the G0 or G1 phase of the cell cycle and inhibits its progression by targeting CDC42." (PMID 34297787, 2021). "In addition to this role in regulating growth factor responses, our data show that by negatively regulating CDC42 activity and actin reorganisation, tumour cell CD99 also modulates the TEM/metastasis of breast cancer." (PMID 34374417, 2021). "For the next common core signaling pathway, the receptor ERBB2, which was mutated in breast cancer, received microenvironment factor CCL28 to activate TF BRCA1 through signaling transduction proteins CDC42 and ARRDC3 in TNBC and non-TNBC." (PMID 33802957, 2021). "Taken together, these findings demonstrated that the uptake of breast cancer-derived EVs by astrocytes is mediated through the non-canonical Cdc42-dependent CLIC/GEEC endocytosis pathway." (PMID 32481745, 2020). "Moreover, RAC1, CDC42, MYL9, MYLK, ABL1, and other genes have been proved to be related to the progress of human breast cancer." (PMID 33306680, 2020). "In the present study, we have shown that DAPT, a GSI, inhibits Notch signaling and then activates PI3K/AKT/Cdc42 signaling by non-canonical Notch pathway, resulting in Cdc42-mediated actin remodeling in migration of breast cancer cells." (PMID 31057403, 2019). "Interestingly, CDC42 was identified from this analysis; cdc42 plays a role in filopodia formation and breast cancer cells expressing DARPP-32 have, in a study looking at Wnt-5A activation of DARPP-32, been shown to have lower cdc-42 activity." (PMID 31740718, 2019). "These do not however describe the entire role of Cdc42, which can also particularly regulate pro-angiogenic factors during breast cancer angiogenesis." (PMID 30754684, 2019). "However, the authors demonstrated that WNT5A-triggered Cdc42 activation inhibits ERK1/2-MMP-9 signaling, resulting in impaired breast cancer migration and invasion." (PMID 30171384, 2018).
breast carcinoma (continued). "To test whether the regulation of miR-29a in breast cancer cells cultured in human insulin medium was directly related to the IGF-1R, CDC42, or p85α, we knocked down the IGF-1R, CDC42, and p85α using siRNA." (PMID 28427228, 2017). "Our data demonstrate that their co-suppression prevents lumen aberration not only in MDCK but also HER2-positive breast cancer BT474 cells without increasing Cdc42 activity." (PMID 26783207, 2016). "To rule out the possibility that the increase in active Cdc42 induced by WNT‐5A is a unique property of MDA‐MB468 breast cancer cells, we employed MDA‐MB231 in our experiments." (PMID 23727359, 2013). "Furthermore, ABCA induces Cdc42 and PAK-1 signaling, which in turn are regulative for breast cancer ER/PR expression in vitro and in vivo." (PMID 23829168, 2013). "The genes belonged to a variety of biological functions such as cell motility and invasion (Cdc42, ITGB2), cell cycle (EGR1, RRM2) or signal transduction (VEGFC), indicating that expression of E-cadh and P-cadh in breast cancer cells have a significant impact on their overall genetic program." (PMID 19257890, 2009). "We also show here that BCAR1 siRNA silencing can function to inhibit invasion of breast cancer cells, even when the cells were not transfected with constitutively activated Cdc42 as was previously demonstrated." (PMID 18435854, 2008). "In breast cancer (BC), the transcription of ITGB1 is activated by CDC42, FOXM1, HIF1α, and EZH2 to support the ability of BC cells to invade and spread." (PMID 38279122, 2024). "High glucose promoted the proliferation of breast cancer cells through the induction of EGFR activation (EGFR phosphorylation) accompanied by the activation of Rac1 and Cdc42, implying the necessity of Rac1 and Cdc42 in the activation of EGFR following high glucose exposure." (PMID 36984785, 2023). "To determine whether Rac/Cdc42 inhibitors affect the viability of macrophages at the therapeutic window, i.e. IC50 of 1.1 μM for EHop-016 and IC50 of 100 nM for MBQ-167 in breast cancer cells, we determined cell viability as measured by an MTT assay on RAW264.7 and THP-1 cell lines." (PMID 37397366, 2023). "NET-DNA-mediated stimulation of breast cancer cells resulted in activation of a NET-CCDC25-ILK signaling axis resulting in the activation of the migration/invasion promoting Rho family GTPases, Rac, and cdc42, while depletion of CCDC25, ILK, or β-parvin reduced Rac1/cdc42 activation." (PMID 35804980, 2022). "In breast cancer, particularly TNBC, NRP-1 is an isoform-specific receptor for VEGF and the VEGF/NRP-1 axis promotes cell proliferation and migration by increasing the activity of cell division control protein 42 homolog (Cdc42) or enhancing the EMT and activation of NF-κB and β-catenin." (PMID 33912463, 2021). "However, MBQ-167 only inhibits Cdc42 activity in breast cancer cells that undergo EMT, rather than non-cancer cells or cancer cells without EMT." (PMID 30754684, 2019). "In this paper, the results showed that DAPT activated Cdc42 but not Rac1, implying that modulation by Cdc42 on F-actin polymerization may be the reason for reduced migration in DAPT treated breast cancer cells." (PMID 31057403, 2019). "Focal adhesion assembly at the mesenchymal-like breast cancer cell leading edge is regulated by integrins that are under Cdc42 regulation, while the integrins that regulate mammary epithelial cell filament cytoskeleton are not directly mediated by Cdc42." (PMID 30754684, 2019). "Injection of RhoA or Cdc42 prevents breast cancer cells from mAb200 (Ras-GAP inhibitor)-induced apoptosis but no additional effects are seen upon Cdc42/RhoA co-injection, which demonstrates that the protective function of Cdc42 in breast cancer results from RhoA activation." (PMID 30754684, 2019).
breast carcinoma (continued). "While a couple of UBA6-dependent ubiquitination substrates, i.e., CDC42, ezrin and CUGBP1, are upregulated in cells with UBA6 depletion, it remains to be determined how downregulation of UBA6 activity impact the proteome of mammary epithelial cells during breast cancer development." (PMID 29152096, 2017). "Other studies on ERα-negative MDA-MB 231 basal-like breast cancer (BLBC) cells have shown that Cdc42 can inhibit the ability of c-Cbl to promote degradation of one of its target proteins, the receptor for epidermal growth factor [EGFR, which is overexpressed in many BLBCs]." (PMID 23606532, 2013). "The depletion of estrogen receptor α (ERα) affects the biomechanical properties of Breast cancer (BC) cells, which is related to the decrease of cytoskeletal proteins (F-actin, FLNA, and α-tubulin) and cytoskeletal regulatory proteins (Rho, Rac1, and Cdc42)." (PMID 34079763, 2021). "In conclusion, our research results indicate that DAPT activates PI3K/AKT/Cdc42 signaling by non-canonical Notch pathway, and the activated Cdc42 promotes the filopodia formation and inhibits lamellipodia assembly, resulting in reduced migration of breast cancer cells." (PMID 31057403, 2019). "Although this model accurately reproduces the typical polarized ruffling dynamics, as observed in breast cancer cells (MDA-MB-231), it only reproduces simultaneous but not the delayed activation of Rac1 and Cdc42." (PMID 37371108, 2023). "Further, CDC42 and POU5F1 gene expression level were relatively higher (>8 fold) when uPAR+/int β1+ compared with uPAR−/int β1− CTC subsets in breast cancer patient without BCBM." (PMID 26631983, 2015). "In addition, Rho GTPases regulate many pathways important in the malignant phenotype, and CDC42 activity (but not RhoA or Rac1) is required for TEM and metastatic progression in prostate and breast cancer models." (PMID 34374417, 2021). "Elongation assays showed that, like DOCK4-depleted cells, cells lacking either DOCK9 or CDC42 did not elongate upon EGF stimulation as control cells, suggesting that DOCK9 and CDC42, together with DOCK4 and RAC1, are essential for the elongation and subsequent intercalation of breast cancer cells." (PMID 38762624, 2024).
gastric cancer (57 papers, 2007 to 2025). A primary or metastatic malignant neoplasm involving the stomach. "Hypermethylation of the MIR137 promoter was shown in gastric cancer tissue, and its suppression induced activation of its target, Cdc42, which is associated with cancer initiation and progression." (PMID 37443682, 2023). "The precise mechanism underlying the MICAL2/MRTF-A-induced activation of CDC42 in gastric cancer cells requires further investigation." (PMID 33842533, 2021). "CDC42 is related to many functions, and it is reported to be associated with the invasion, migration, and proliferation of gastric cancer cells and cervical tumors." (PMID 31396530, 2019). "Expression of Cdc42 is significantly increased in gastric cancer tissues and is associated with post-transcriptional regulation." (PMID 29596304, 2018). "LncRNA DSCR8 mediates miR-137/Cdc42 to regulate gastric cancer cell proliferation, invasion and cell cycle as a competitive endogenous RNA." (PMID 37858131, 2023). "Through miR-148b-3p, Rac1 and Cdc42 can be activated, which directly affect the motility of gastric cancer cells, and can serve as a new treatment strategy specific to gastric cancer." (PMID 37274025, 2023). "Our experiments using Cdc42-, Rac1-, and Rho-blocking agents revealed that the Cdc42 GTPase inhibitor resulted in a dose-dependent decrease in cell attachment of all four gastric cancer cell lines." (PMID 35723363, 2022). "Overall, these findings demonstrated that MICAL2 promotes E-cadherin degradation and gastric cancer cell migration in a Cdc42 activity-dependent manner." (PMID 36064550, 2022). "In this context, the role of Cdc42 in tumor invasion and metastasis of gastric cancer cells should be investigated in specimens derived from patients with cancer." (PMID 35723363, 2022). "Further, the involvement of Cdc42 in the laminin 511-E8 fragment-induced enhanced adhesion of gastric cancer cells was suggested." (PMID 35723363, 2022). "Here, our data suggested that the MICAL2/MRTF-A complex promotes gastric cancer cell migration through the CDC42 pathway, at least partially." (PMID 33842533, 2021). "In contrast, our results showed that MICAL2 overexpression resulted in a significant increase in Cdc42 activation in gastric cancer cells." (PMID 34650666, 2021). "We have recently shown that MICAL-L2, a member of the MICAL protein family, enhances the migratory ability of gastric cancer cells via regulating EGFR stability in a Cdc42-dependent manner." (PMID 34650666, 2021). "Combined, these findings demonstrated that Cdc42 activation is required for MICAL2-mediated YAP nuclear translocation in gastric cancer cells." (PMID 34650666, 2021). "Collectively, our results showed that MICAL2 has a promotive effect on gastric cancer cell proliferation through ROS generation and Cdc42 activation, both of which independently contribute to YAP dephosphorylation and its nuclear translocation." (PMID 34650666, 2021). "Further research discovered that increased miR-137 expression and inactivation of Cdc42 promoted tumour cell apoptosis or cell cycle arrest at G1 phase, thus suppressing the development of gastric cancer." (PMID 33413360, 2021). "Recently, CDC42, an important Rho GTPase family member, was shown to have an active role in gastric cancer migration and invasion." (PMID 33842533, 2021). "In this study, we showed that FARP1 overexpression was significantly associated with lymphatic invasion, lymph metastasis, and poor prognosis in patients with advanced gastric cancer, and that it promoted gastric cancer cell motility by activating CDC42." (PMID 32029704, 2020). "Taken together, GINS4 plays key roles in cell proliferation, cell cycle, apoptosis, migration and invasion of gastric cancer through activating Rac1 and CDC42 and their downstream signaling pathways: MAPK/ERK pathway, PI3K/AKT pathway and PTEN pathway." (PMID 31754397, 2019).